MYC (MYC proto-oncogene, bHLH transcription factor)
Diseases named in the same sentence as MYC in open-access papers (continued):
Sharing a sentence is not in itself a finding about the gene and the disease.
breast cancer (continued). "Besides MYC itself, we find upregulation of other breast cancer stem cell factors (SOX2, SOX18, THY1, EYA1, GLI2, SALL1, GLIS1, CXCR4), suggesting that MYC HME cells adopt a stem-like state." (PMID 31942031, 2020). "For this study, we examined tumors in three large breast cancer patient cohorts (TCGA, METABRIC and GSE124647) and their MYC targets v1 and MYC targets v2 scores and the correlation with cell proliferation, clinical and pathologic features, survival differences, and immune cell infiltration." (PMID 33143224, 2020). "Nuclear AURKA acts as a transcriptional factor that activates the MYC promoter to enhance breast cancer stem cell phenotype independent of its kinase activity." (PMID 31920463, 2020). "MYC is expressed in human and mouse macrophages cultured in vitro, but MYC expression in breast cancer TAMs has not been explored." (PMID 32685002, 2020). "DOT1L interacts with c-MYC and p-300 for activating EMT in breast cancer." (PMID 32257110, 2020). "A strong correlation between MKK3 overexpression, activation of its binding partner and major oncogene MYC, and worsened clinical outcomes suggests the MKK3-MYC protein–protein interaction as a new promising target to reduce racial disparity in breast cancer survival." (PMID 32873298, 2020). "It has been reported that melatonin could downregulate the expression of MYC and upregulate the expression of BAX to stimulate the apoptotic effects in breast cancer cells." (PMID 32689938, 2020). "Lastly, our score is dependent on gene expression data, which is not currently included in the standard workup of breast cancer, and will therefore limit current clinical use of the MYC targets score." (PMID 33143224, 2020). "Both MYC and TBX3 play important roles in breast cancer and BCSCs." (PMID 33217982, 2020). "Additionally, proteins involved in the c-MYC and TGF-β pathways were found in higher quantities in YWBC patient EVs, both of which are well established in the development and progression of breast cancer." (PMID 33225939, 2020). "Furthermore, epithelial-mesenchymal transition (SNAIL2) and proto-oncogenes (MYC and HER2) were found to be upregulated in the DMBA-induced breast cancer tissues." (PMID 33178325, 2020). "MYC and MAX RNA were detected in circulating breast cancer monocytes (KRT7+, CD11b+, CSF1R+), whole breast cancer tissue (KRT7+, CD11b+, CSF1R+), and isolated breast cancer tumor infiltrating macrophages (KRT7 negative or low, CD11b+, CSF1R+), supporting a potential role for MYC in human TAMs." (PMID 32685002, 2020). "We next analyzed the relationship between the expression of Cyclin E, c-MYC, Cdc25A, and markers of replication stress with disease-free survival (DFS), recurrence-free survival (RFS) or overall survival (OS) in our breast cancer cohort (n = 379) using Cox regression analyses." (PMID 32964114, 2020). "The positive correlation of the transcript levels among PRKD3, ERK1 and c‐MYC in the human breast cancer tissues was not significant, supporting that PRKD3 activated ERK1/c‐MYC axis independent of up‐regulating the transcript levels of the ERK1 and c‐MYC." (PMID 31944568, 2020). "Therefore, our analyses suggest that MYC is an important target of CORO2A and that CORO2A acts through this factor to regulate the cell migration, cell cycle, and proliferation capacity of breast cancer." (PMID 32695665, 2020). "Also, low correlation between copy numbers and gene expression levels (r = 0.093) was observed for MYC in CMT, in contrast to human breast cancers (r = 0.247)." (PMID 32680987, 2020). "c-MYC (Cellular MYC Proto-Oncogene, BHLH Transcription Factor) is one of the most upregulated oncogenes in several types of cancer and has been reported to play variable roles in different molecular subtypes of breast cancer." (PMID 32340192, 2020).
breast cancer (continued). "Finally, expression of P5CS, PYCR1/2/L is increased by c-MYC and PI3K signaling in luminal B breast cancer as was previously shown in cultured cancer cells after ectopic expression of c-MYC." (PMID 32500033, 2020). "In addition, the proliferation of the breast cancer cells and the tumour growth in xenograft mouse models were promoted by both the PRKD3 overexpression and the ERK1/c‐MYC axis activation." (PMID 31944568, 2020). "Similarly, it will interesting to trace the effect of prominent tumor factors in breast cancer, such as SCRIBL/MYC or the Hippo pathway on overall tissue integrity and promotion of tumor growth in a none tissue wide expression setting." (PMID 32690136, 2020). "Taken together, our studies suggested that PRKD3 regulated phosphorylation of ERK1, not ERK2, and then ERK1 stabilized c‐MYC by phosphorylation, leading to promote the proliferation of the breast cancer cells." (PMID 31944568, 2020). "In addition, Immunofluorescence staining showed that p‐ERK1/2 (Thr202/Tyr204), p‐c‐MYC (Ser62) and c‐MYC were down‐regulated by knocking out PRKD3 in breast cancer cells." (PMID 31944568, 2020). "In breast cancer, HN1 can enhance MYC expression to contribute to cancer progression." (PMID 32608539, 2020). "Interestingly, in breast cancer cells, a tumor suppressor role was recently ascribed to the PVT1 promoter, which is proposed to act as a DNA boundary element that insulates MYC from its downstream enhancers." (PMID 31338324, 2019). "Moreover, miR-9, which is directly bound and upregulated by MYC and MYCN in breast cancer cells, directly targets CDH1, leading to increased cell motility and invasiveness." (PMID 31208279, 2019). "Thus, high expression levels of MYC and anti-apoptotic BCL-2 proteins are common features in breast cancer." (PMID 30728358, 2019). "Previous studies have also identified the amplicon at 8q24.3 by representational difference analysis as a location of oncogenic alterations in breast cancer that can occur independent of neighboring MYC amplifications." (PMID 31216036, 2019). "Together with MYC, lncRNA EPIC1 co‐occupies the promoters of > 97% of EPIC1‐regulated genes involved in cell cycle progression, and thereby regulates transcriptional activity of these genes in breast cancer cells." (PMID 30451365, 2019). "In our breast cancer TMA set high MYC status did not correlate with high BIM expression or high AMPK activity; however, high AMPK activity correlated with high BIM expression." (PMID 30728358, 2019). "In the current study, we found that MYC DNA amplification was not equivalent to high expression of MYC mRNA in either the whole breast cancer or TNBC cohort." (PMID 31905596, 2019). "AR also enhanced MYC transcriptional activity by phosphorylating MAD1 and promoting activation of the HER2/HER3 signaling pathway, leading to increased levels of MYC/MAX heterodimers that ultimately promoted breast cancer growth." (PMID 31413736, 2019). "Very different it is the case of SIN3B (SIN3 transcription regulator family member B), a well known protein that interacts with MYC (MYC proto-oncogene, BHLH transcription factor), which was observed promoting cancer progression and metastasis in breast cancer in accordance with our data." (PMID 31159827, 2019). "For example, complete tumor elimination has been reported in MYC-induced osteosarcoma and lymphoma, while conversion of tumor cells to a dormant state has been reported for MYC-induced HCC and breast carcinoma, where these dormant cells can revert back to the tumor state upon oncogene reactivation." (PMID 31515263, 2019). "Interestingly, amplification ofoncogenes such as n-MYC in neuroblastoma(Brodeur etal., 1984)or HER2/NEU amplification in breast carcinoma was shown to predict poor prognosisin cancer patients." (PMID 31410080, 2019).
breast cancer (continued). "Surprisingly, despite the central role of Cyclin D1 in cell cycle regulation, mice lacking Cyclin D1 are viable and resistant to HER2(neu)-induced breast cancers (but not to breast cancers induced by MYC)." (PMID 29670855, 2018). "Finally, breast cancer patients with both CLK2 high expression and MYC amplification showed poor prognosis in the clinical data." (PMID 29769258, 2018). "We began the study with evaluating MYC, DNMT3A and miR‐200b levels in breast cancer tissues." (PMID 30324719, 2018). "In addition, ZNF121 and MYC regulate each other's protein expression or stability, and ZNF121 indeed regulates cell proliferation, apoptosis, and likely breast cancer development." (PMID 30524945, 2018). "Association of MYC, PVT1, or FAM84B transcript levels with any of the breast cancer risk alleles has not been reported." (PMID 30526553, 2018). "The restoration of miR-340 in breast cancer cell lines lacking this miRNA inhibited cell growth by the activation of the Wnt pathway and the MYC expression." (PMID 30038718, 2018). "Unfortunately, some frequent CNAs of breast cancer (e.g., MYC, CCND1 amplification) reported previously were not included in our gene panel." (PMID 30086764, 2018). "Although the cancer gene MYC is a very attractive therapeutic target in the treatment of breast cancer, the direct inhibition of the MYC gene is still a great challenge and has not yet provided a clinically effective drug to target it31." (PMID 29855504, 2018). "The situation appears to be different in basal-like breast cancers since BCL-XL expression is neither positively correlated to MYC expression nor negatively with that of pRB." (PMID 29066722, 2017). "Combination therapy of MYC signal pathway inhibitors would improve clinical outcomes of breast cancer patients, especially for patients with negative hormone receptors." (PMID 29212204, 2017). "Suppression of MYC compromised the TIM-induced invasiveness and migration of breast cancer cells." (PMID 28464854, 2017). "In breast cancer models PVT1 RNA levels correlate with MYC protein, yet PVT1 and c-MYC are not always co-amplified." (PMID 28747406, 2017). "Our method identified not only many known cancer genes such as CCND1, MYC, ERBB2, RB1 and BRCA1 in breast cancer but also many novel protein‐coding genes as well as non‐coding RNAs that may contribute to carcinogenesis." (PMID 28719033, 2017). "Since frequent MYC amplification and CDKN2A/B deletions were also seen in a recently established bank of human breast cancer PDXs, these genetic events may contribute to efficient engraftment." (PMID 28430642, 2017). "This suggests that amplification of this lncRNA alone (even without MYC) can promote tumorigenesis in breast cancer by increasing MYC expression, which has been proposed to occur by protein stabilization." (PMID 28747406, 2017). "Breast cancer Met-1 cells were transducted with a DACH1 expression vector resulting in an ∼4.5-fold increase in DACH1 expression and subsequent reduction of CSC markers CD44, KLF4 and MYC as well as EMT markers including FN1 and VIM by mRNA analysis." (PMID 28659634, 2017). "To investigate these mechanisms in breast cancer, we sequenced the TERT promoter, evaluated TERT copy number changes and assessed the expression of the MYC oncogene, a known transcriptional TERT regulator, in two breast cancer cohorts comprising a total of 122 patients." (PMID 29100407, 2017). "Additionally, lncRNA BCAR4 controls the epigenetic regulation of Hedgehog/GLI2 transcriptional activation in support of breast cancer progression, whereas CCAT2 modulates WNT and MYC activity in colon cancer leading to increased metastasis." (PMID 27756687, 2017). "Treatment with CDK1/2 inhibitors or depletion of CDK2 efficiently inhibit growth and/or induce apoptosis in triple negative/basal breast cancer, MYCN-amplified neuroblastoma and myeloid leukemia cell lines and in mouse models of MYC-driven lymphoma and liver cancer." (PMID 28665315, 2017).
breast cancer (continued). "Moreover, MYC showed a much lower CN-GE correlation coefficient than SQLE in both breast and ovarian cancers (ρ = 0.11 in breast cancer and 0.40 in ovarian cancer, D top right)." (PMID 26777065, 2016). "Concordantly, the expression levels of multiple downstream targets of Wnt/β-catenin signaling, namely cyclin D1, c-MYC, TCF4 and LEF1, and nuclear β-catenin, were increased in the miR-1229–overexpressing breast cancer cells but decreased in the miR-1229–silenced breast cancer cells." (PMID 26992223, 2016). "Univariate Kaplan Meier analysis of four groups in the whole, as well as the ER+ patients showed that c-MYC and ADA3 combinatorial phenotypes showed significantly different breast cancer specific survival with c-MYC-high and ADA3-Low subgroup had the worst outcome." (PMID 27852327, 2016). "Other than described in angiosarcomas, breast included, MYC gene status by either method in this study did not predict for MYC mRNA and protein over-expression, in line with previous observations in breast carcinomas." (PMID 27184134, 2016). "Since this subtype is not normally associated with MYC overexpression, it is possible that Luminal A breast cancers retain sensitivity to MYC protein abundance, unlike MYC-independent breast cancer subtypes." (PMID 25669969, 2015). "Tumours in which c-MYC immunoreactivity was detected in <10% of cells were considered to be negative for expression (8 radiogenic (44%) and 16 sporadic breast cancer cases (48%))." (PMID 25531321, 2015). "We conclude from these observations that our initial findings from the screen using MCF10A-MYCER cells can be extended to the T47D breast cancer cell line in which MYC expression was not experimentally altered and independent of ER activation." (PMID 25669969, 2015). "Similarly, the top hub TFs we found in the integrated network such as SP1, SP2, TCF12, MYC, JUN and EGR2, were also well-known regulators in breast cancer." (PMID 26763900, 2015). "Additionally, we show breast cancer specific MYC genes that are statistically differentially expressed between MCF7-eveR and MCF7-parental, suggesting the increased MYC is functional in this setting." (PMID 25537515, 2015). "Neratinib and GSK-1070916 show synergy in the MYC-amplified breast cancer line AU-565, but not in the wild-type control BT549." (PMID 26018524, 2015). "Interestingly, our analysis suggests that MYC and FBXW7 expression are mildly but significantly positively correlated, specifically in the Luminal A-subtype of breast cancers." (PMID 25669969, 2015). "Our findings reveal a unique role for MYC in regulating cell fate through the UPR, and suggest that targeting glutamine metabolism may be a novel strategy in endocrine resistant breast cancer." (PMID 25339305, 2014). "MYC regulation of GLS and GLUL in antiestrogen resistant breast cancer cells was unexpected." (PMID 25339305, 2014).
breast cancer (continued). "While in prostate cancer cells, MYC knockdown was shown to decrease GLS and increase GLUL protein levels, in our antiestrogen resistant breast cancer cell models (LCC9, LCC2, and LY2) we observed the reverse effect – MYC knockdown increased GLS and decreased GLUL protein levels." (PMID 25339305, 2014). "In addition, a previous study has shown that miR-9, which is directly bound and upregulated by MYC and MYCN in breast cancer cells, directly targets CDH1, leading to increased cell motility and invasiveness." (PMID 24520301, 2014). "Reduced expression of active β-catenin and its downstream target gene c-MYC were detected in DACT1-expressing MB231 cells, suggesting that DACT1 antagonizes Wnt/β-catenin signaling by decreasing active β-catenin levels in breast cancer." (PMID 23497530, 2013). "To determine whether cohesin is required for estradiol-mediated activation of MYC in other ER-positive cell lines, we used siRNA to deplete RAD21 in T47D breast cancer cells." (PMID 23145106, 2012). "It is unclear why RAD21 binding is enriched in MCF7 but not the other breast cancer cells, but it is possible that interaction between the C SNP enhancer and the MYC promoter contributes to regulation of MYC in MCF7 cells." (PMID 23145106, 2012). "MYC mRNA was not significantly altered in breast cancer or in thyroid gland cancer, compared with normal tissue." (PMID 21226903, 2011). "In our in silico analysis, we recently showed that, apart from repressing MYC, ras, and HMGA2, let-7 may also target CYP19A1, ESR1, and ESR2, thereby potentially blocking estrogen signalling in er-positive breast cancers." (PMID 20179807, 2010). "Interestingly, in most breast cancer cell lines, the expression of TRPS1 was high compared to the expression levels of EIF3S3 and MYC." (PMID 14997205, 2004). "Similarly, our findings reveal miR-32-5p as a novel regulator of c-MYC-driven proliferation in HER2-negative breast cancer, further supporting the potential of targeting non-canonical pathways in aggressive subtypes and can be further Clinical Implications." (PMID 40711670, 2025). "In endocrine-resistant ERα+ breast cancer, CDK9 mediates hyperphosphorylation of serine-2 in the RNA Pol II CTD at the c-MYC gene promoter, resulting in transcriptional elongation and overexpression of c-MYC, which drives estrogen-independent growth of resistant cancer cells." (PMID 40949156, 2025). "MiR-155’s metabolic effect was further confirmed in human breast cancer cell lines; in addition, miR-155-high tumors displayed higher glucose uptake in patient samples seen through PET images, with miR-155 correlating negatively and positively with FOXO3a and MYC, respectively." (PMID 40126351, 2025). "In immunodeficient mouse model with breast cancer, chronic stress-induced epinephrine activates key enzyme LDHA to produce lactic acid, forming an acidic microenvironment to facilitate USP28-mediated deubiquitination of MYC, resulting in enhanced cancer stemness." (PMID 39054537, 2024).